ANO1 (anoctamin 1)
Diseases named in the same sentence as ANO1 in open-access papers (continued):
Sharing a sentence is not in itself a finding about the gene and the disease.
Stroke (10 papers, 2013 to 2025). Sudden impairment of blood flow to a part of the brain due to occlusion or rupture of an artery to the brain. "However, the role of lncRNA ENST00000530525 and the regulatory mechanism linking lncRNAs and ANO1 signaling in stroke remain enigmatic." (PMID 35754821, 2022). "Thus, we further speculated that lncRNA ENST00000530525 and ANO1 are involved in the pathology of stroke." (PMID 35754821, 2022).
ischemic stroke (8 papers, 2019 to 2025). A stroke disorder caused by obstruction of blood flow to the brain, due to thrombotic (local blood clot formation) or embolic (due to a blood clot or other material traveling from another site) event. "Researchers found that ANO1 is expressed in brain capillary endothelial cells (BCECs) and is upregulated after ischaemic stroke caused by middle cerebral artery occlusion or under hypoxia." (PMID 41210337, 2025). "A recent study demonstrated that the lncRNA ENST00000530525 may affect ANO1 expression by recruiting transcription factors or enhancers after ischaemic stroke." (PMID 41210337, 2025). "In addition, CaCCinh-A01 also preserves BBB integrity, attenuates brain infract size and neurological deficits after ischemic stroke, indicating that ANO1 may become a potential target for ischemic stroke." (PMID 36935741, 2023).
chronic obstructive pulmonary disease (7 papers, 2017 to 2025). A chronic and progressive lung disorder characterized by the loss of elasticity of the bronchial tree and the air sacs, destruction of the air sacs wall, thickening of the bronchial wall, and mucous accumulation in the bronchial tree. "Evidence suggests that ANO1 dysfunction is an emerging pathogenesis of MIRI, cardiac arrhythmias, and cardiac fibrosis." (PMID 41210337, 2025).
endothelial dysfunction (7 papers, 2018 to 2025). In vascular diseases, endothelial dysfunction is a systemic pathological state of the endothelium (the inner lining of blood vessels) and can be broadly defined as an imbalance between vasodilating and vasoconstricting substances produced by (or acting on) the endothelium. "Endothelial dysfunction, including endothelial proliferation, apoptosis, migration, and angiogenesis, is involved in the pathogenic process of various vascular diseases, in which ANO1 plays a multifaceted role." (PMID 41210337, 2025). "To test whether endothelial dysfunction is responsible for the increased contraction of tail arteries from ANO1 heterozygous mice, we compared their contractile responses after endothelium removal." (PMID 33245843, 2020).
colitis (5 papers, 2015 to 2022). Inflammation of the colon. "The Ano1-deficient colons became edematous under basal conditions and had a greater susceptibility to dextran sodium sulfate-induced colitis." (PMID 31383845, 2019). "The ANO1-deficient mice accumulated fluid within colonic tissues, which increased their susceptibility to colitis." (PMID 31383845, 2019). "Ano1 disruption in the colon led to much greater susceptibility to colitis." (PMID 31383845, 2019). "We thus conclude that ANO1 is necessary for cAMP- and carbachol-induced Cl− secretion in the intestine, which is essential for the protection of the intestinal epithelium from colitis." (PMID 31383845, 2019). "The findings point to ANO1 activation as a potential therapeutic strategy for treating colitis." (PMID 31383845, 2019). "ANO1 is vital for the protection of intestinal epithelium from colitis, whereas its expression was significantly decreased in the DSS-induced colitis mice." (PMID 35893911, 2022). "If the balance between depolarizing (activation of ANO1 channels in ICC) and hyperpolarizing (activation of SK3 channels in PDGFRα+ cells) is disrupted, as occurs in DSS colitis, one might expect greater depolarization and greater contractile responses to PAR1 activation." (PMID 36202914, 2022).
diabetes (5 papers, 2017 to 2025). "No nonspecific staining was found in this study, suggesting that Ano1 is a more reliable marker to monitor the ICC changes in diabetes and EA models." (PMID 29854081, 2018). "Ano1 is a reliable marker to detect ICC changes in diabetes; low- and high-frequency EA at acupoint ST36 can protect the networks of ICC possibly via normal activation of mSCF/KIT-ETV1 signaling." (PMID 28203258, 2017). "However, Ano1 immunoreactivity has not been observed in diabetes associated with loss of c-Kit positive ICC." (PMID 28203258, 2017).
ischemia (5 papers, 2019 to 2025). A hypoperfusion of the BLOOD through an organ or tissue caused by a PATHOLOGIC CONSTRICTION or obstruction of its BLOOD VESSELS, or an absence of BLOOD CIRCULATION. "Previous research has shown that increased ANO1 expression can raise the density of calcium-activated chloride channels in ischemic hearts, causing arrhythmias triggered by ischemia." (PMID 40894480, 2025).
liver cancer (5 papers, 2023 to 2025). An epithelial or non-epithelial malignant neoplasm that arises from the liver. "In addition, ANO1 promotes metastasis of liver cancer and ovarian cancer by activating the phosphatidylinositol 3 kinase/protein kinase B signaling pathway." (PMID 38352864, 2024). "Notably, INMT, ANO1 and GCNT3 have recently been implicated in other types of cancer, which could potentially impact the outcomes of liver cancer." (PMID 39628446, 2024).
non-small cell lung carcinoma (5 papers, 2015 to 2025). A group of at least three distinct histological types of lung cancer, including non-small cell squamous cell carcinoma, adenocarcinoma, and large cell carcinoma. "The goal of this study was to investigate whether Ca2+-activated Cl- channel (CaCC) ANO1 or TMEM16A, originally identified from airway epithelial cells, is involved in progression of non-small-cell lung carcinoma that is typical of epithelial lung cancer." (PMID 26305547, 2015). "In non-small cell lung cancer, SMYD3 binds to the anoctamin-1 (ANO1) promoter region, which is enriched with H3K4me3, thereby increasing ANO1 transcription and regulating cancer cell proliferation." (PMID 39482529, 2024).
ovarian carcinoma (5 papers, 2019 to 2025). A malignant neoplasm originating from the surface ovarian epithelium. "Studies have shown that ANO1 is significantly overexpressed in epithelial ovarian cancer cells, with its upregulation strongly associated with higher FIGO (International Federation of Gynecology and Obstetrics) stages and lower differentiation grades." (PMID 40356890, 2025). "In ovarian cancer, ANO1 knockdown reduces PI3K/Akt phosphorylation, and the use of specific inhibitors can suppress ANO1-mediated ovarian cancer cell growth by targeting PI3K/Akt signaling." (PMID 40356890, 2025). "Our recent results showed that ANO1 mRNA expression in PBMCs is upregulated in preoperative patients with ovarian cancer and decline of ANO1 mRNA expression is noted post-operation." (PMID 31266974, 2019). "Therefore, ANO1 plays a critical role in ovarian cancer progression, correlating with poor prognosis and advanced stages." (PMID 40356890, 2025). "Furthermore, downregulation of ANO1 reduces PI3K/Akt phosphorylation, inhibiting ovarian cancer cell growth by disrupting the PI3K/Akt signaling pathway." (PMID 40356890, 2025).
sarcoma (5 papers, 2011 to 2022). A usually aggressive malignant neoplasm of the soft tissue or bone. "However, HIF-2α may also inhibit sarcoma growth in an ANO1 and mTORC1-independent fashion." (PMID 26837714, 2016). "However, since Matrigel is heterogeneous ECM mixtures isolated from Engelbreth-Holm-Swarm mouse sarcoma, key ECM substances triggering the demethylation of ANO1 CpG islands in HSG cells should be further specified." (PMID 31847128, 2019).
Arrhythmia (4 papers, 2022 to 2025). Any cardiac rhythm other than the normal sinus rhythm. "Furthermore, the activation of ANO1 in cardiac fibroblasts affects the electrophysiological activity of cardiomyocytes via gap junctions, ultimately leading to ectopic pacing, which may be an underlying mechanism related to arrhythmia." (PMID 41210337, 2025). "Anoctamin-1 (ANO1), a calcium-activated chloride channels (CaCCs) protein is increased during ischaemia and is suggested to contribute partly to the development of ischaemia-induced arrhythmias." (PMID 41462954, 2025).
benign prostatic hyperplasia (4 papers, 2016 to 2025). A non-cancerous nodular enlargement of the prostate gland. "Recently, Cha and colleagues demonstrated that ANO1 is essential for benign prostatic hyperplasia (BPH)." (PMID 26811235, 2016). "A recent report indicates that ANO1 is involved in the development of benign prostatic hyperplasia (BPH), and pharmacological inhibition of ANO1 inhibits prostate enlargement and reduces histological abnormalities in the BPH rat model." (PMID 27219012, 2016).
Brain Infarct (4 papers, 2019 to 2024). "Furthermore, Ca2+-activated TMEM16A (also known as anoctamin-1) function as Cl− channels, and open in response to cerebral infarction." (PMID 39130645, 2024).
Insulin resistance (4 papers, 2020 to 2024). Increased resistance towards insulin, that is, diminished effectiveness of insulin in reducing blood glucose levels. "Spliceosome pathway has a role in the regulation of alternative splicing in insulin resistance cases by aberrantly spliced genes like ANO1, GCK, SUR1, VEGF." (PMID 37529091, 2022). "In mice with hepatocyte‐specific ANO1 overexpression, obesity and insulin resistance induced by a high‐fat diet (HFD) were markedly increased, whereas the hepatic steatosis, adipogenesis, and inflammation induced by a HFD were reduced when ANO1 was specifically knocked down." (PMID 38685684, 2024).
liver diseases (4 papers, 2022 to 2025). "Recently, several investigators found that ANO1 was downregulated in portal smooth muscle cells (PVSMC) from bile duct ligation mice with cirrhotic portal hypertension via increased AngII, followed by a reduction in spontaneous contractions." (PMID 41210337, 2025). "In this paper, we reviewed the role of ANO1 in the development of several liver diseases and provided strategies or directions for the diagnosis and treatment of liver diseases." (PMID 38685684, 2024). "Several studies have shown that ANO1 can also be involved in the pathogenesis of liver diseases by interacting with other proteins." (PMID 38685684, 2024). "More research is necessary to establish whether ANO1 is a viable candidate for the treatment of portal hypertension." (PMID 41210337, 2025). "Thus, regulating ANO1 could provide a new therapeutic strategy for liver diseases characterized by impaired bile flow (e.g. cholestasis)." (PMID 38685684, 2024). "In addition, ANO1 is involved in the regulation of multiple liver disease signalling pathways." (PMID 38685684, 2024).
smooth muscle tumor (4 papers, 2020 to 2025). A benign or malignant myomatous neoplasm arising from smooth muscle. "Most GISTs stain for KIT protein (CD117; 95%) and anoctamin-1 (DOG-1; 98%), but most do not stain for desmin, a biomarker of smooth muscle tumors." (PMID 32264886, 2020).
soft tissue tumors (4 papers, 2014 to 2025). "Other markers, such CD34, CD117, myogenin, and DOG1 (discovered on GIST, also known as anoctamin 1), have also been proposed to play a significant role in identifying soft tissue tumors." (PMID 41262926, 2025).
Tracheomalacia (4 papers, 2014 to 2021). "In addition, Ano1 knock-out mice display a pronounced tracheomalacia, accumulate mucous in the tracheal lumen and die during the early postnatal period further delineating an important function of ANO1 during fetal development." (PMID 25910246, 2015).
airway hyperresponsiveness (3 papers, 2019 to 2025). "High expression levels of ANO1 in ASM have been linked to airway hyperresponsiveness." (PMID 40356890, 2025).
Anxiety (3 papers, 2020 to 2026). Intense feelings of nervousness, tension, or panic often arise in response to interpersonal stresses. "Previously, we reported that mice with conditional ablation of TMEM16A (ANO1) in cholinergic neurons of the medial habenula (ANO1 cKO) exhibit behavioral patterns indicative of anxiety, reduced social motivation, and anhedonia." (PMID 41527097, 2026).
epilepsy (3 papers, 2019 to 2023). A brain disorder characterized by episodes of abnormally increased neuronal discharge resulting in transient episodes of sensory or motor neurological dysfunction, or psychic dysfunction. "Because many brain disorders, such as autism, schizophrenia, and epilepsy, are related to defects in brain development, understanding the molecular mechanisms underlying the ANO1-dependent RGC functions may contribute to solving these mental disorders." (PMID 31147466, 2019).
Fibroadenoma (3 papers, 2015 to 2023). A benign tumor of the breast characterized by the presence of stromal and epithelial elements. "In contrast, we only detected Ano1 expression in 13.0% of 46 fibroadenoma samples." (PMID 25961581, 2015). "In contrast, Ano1 was found in 6 (13.0%) of 46 fibroadenoma samples." (PMID 25961581, 2015).
fibrosis (3 papers, 2017 to 2022). the formation of excess fibrous connective tissue in an organ or tissue in a reparative or reactive process. "After ANO1 over-expression, cardiac fibrosis was reduced in vitro and in vivo." (PMID 28539652, 2017).
invasive carcinoma (3 papers, 2015 to 2023). A carcinoma that is not confined to the epithelium, and has spread to the surrounding stroma. "In an attempt to accomplish this, ANO1 protein expression and gene amplification were analysed on a set of laryngeal precancerous lesions, and molecular data correlated with the risk of progression to invasive carcinoma." (PMID 26498851, 2015).
lung squamous cell carcinoma (3 papers, 2015 to 2023). "In tissue specimens from squamous cell lung carcinoma, 6 of 40 (15%) were stained ANO1 positive." (PMID 26305547, 2015).
metastatic tumors (3 papers, 2014 to 2024). "The rate of ANO1 expression was higher in metastatic tumors than in non-metastatic tumors, and the difference was statistically significant (Chi-square test, P<0.05)." (PMID 24316695, 2014).
Sjögren’s syndrome (3 papers, 2019 to 2024). "Problems with exocrine gland function in patients with Sjögren’s syndrome as well as the low TRPV4 expression levels in patients with AIGA suggest that TRPV4 could be a key molecule involved in these diseases and that novel treatment strategies could target TRPV4 and/or ANO1." (PMID 38963781, 2024).
acute pancreatitis (2 papers, 2023 to 2025). An acute inflammatory process that leads to necrosis of the pancreatic parenchyma. "This cascade may contribute to the pathogenesis of acute pancreatitis, suggesting that inhibiting ANO1 could be a promising therapeutic strategy." (PMID 40356890, 2025). "In acute pancreatitis, ANO1 may increase intracellular Ca2+ levels and stimulate IL-6 secretion." (PMID 40356890, 2025). "ANO1 expression was only reported on the apical membrane of pancreatic acinar cells, in which HCO3− secretion via ANO1 attenuated the pH shift during acute pancreatitis." (PMID 37380797, 2023).
Allergy (2 papers, 2024). An allergy is an immune response or reaction to substances that are usually not harmful. "ANO1, which is associated with allergy and itch signaling, was also upregulated with IL-13 treatment [log2 (fold change) of 2.45]." (PMID 38344408, 2024).
Anaplastic thyroid carcinoma (2 papers, 2019 to 2023). "Anaplastic thyroid carcinoma appears to acquire its undesirable traits and aggressiveness through ANO1 overexpression; ANO1 knockdown greatly reduces the tumor’s aggressive behavior." (PMID 36836529, 2023). "Based on these findings, we also suggest the possibility of using ANO1 as a novel biomarker to determine the level of aggressiveness in anaplastic thyroid carcinoma." (PMID 31489251, 2019).
autosomal dominant polycystic kidney disease (2 papers, 2021 to 2023). Autosomal dominant form of polycystic kidney disease. "Furthermore, our observation that Ani9 inhibited proliferation of HaCaT cells is in agreement with another report that Ani9 inhibited the increased growth of cysts in mice with autosomal dominant polycystic kidney disease by upregulation of ANO1." (PMID 34281197, 2021).
cardiac hypertrophy (2 papers, 2022 to 2023). "Inversely, ANO1 overexpression significantly attenuates pressure-overload-induced maladaptive cardiac hypertrophy, fibrosis, and cardiomyocyte apoptosis in ANO1 TG mice hearts compared to WT mice counterparts." (PMID 35624741, 2022).
cholangiocarcinoma (2 papers, 2023 to 2024). A carcinoma that arises from the intrahepatic biliary tree (intrahepatic cholangiocarcinoma) or from the junction, or adjacent to the junction, of the right and left hepatic ducts (hilar cholangiocarcinoma). "Kulkarni et al122 reported that ANO1 can interact with the mTOR pathway to regulate the cytoskeleton, survival, proliferation, and migration in cholangiocellular carcinoma, but the specific underlying mechanisms need to be further investigated." (PMID 38685684, 2024). "In addition, Kulkarni et al122 reported that ANO1 can interact with mTOR to regulate the cytoskeleton, survival, proliferation and migration in cholangiocarcinoma." (PMID 38685684, 2024).
congenital megacolon (2 papers, 2023 to 2024). "Abnormal expression or dysfunction of ANO1 is associated with the pathogenesis of various diseases, including diabetic gastroparesis, congenital megacolon, gastroesophageal reflux, and chronic constipation." (PMID 38831987, 2024).
Constipation (2 papers, 2021 to 2025). Infrequent or difficult evacuation of feces. "NAR increased the levels of ANO1 and c-Kit in the colon tissue of mice with Lop-induced constipation mice." (PMID 40599805, 2025). "In this study, IHC was used to assess the impact of NAR on ICCs, with a focus on changes in ANO1 and c-Kit protein levels in the colons of mice with Lop-induced constipation after they were treated with NAR." (PMID 40599805, 2025). "ANO1 is closely associated with the generation of ICC pacemaker currents and can regulate the excitability of intestinal smooth muscle in patients with constipation." (PMID 40599805, 2025).
dry eye (2 papers, 2021 to 2023). "Therefore, a reduction in ANO1 protein expression can result in various adverse effects, such as dry mouth, dry eye, low blood pressure (hypotension) and intestinal dysmotility; nonetheless, this reduction presents with a considerable advantage in terms of anticancer effects." (PMID 34281152, 2021).
endometrial cancer (2 papers, 2021 to 2024). Primary or metastatic malignant neoplasm involving the endometrium (mucous membrane that lines the endometrial cavity). "For instance, researchers found that Prostaglandin D2 Synthase (PTGDS) predicted poor survival, while ANO1 might be a potential marker for good prognosis in endometrial cancer by WGCNA." (PMID 33936173, 2021). "Additional co-expression analysis studies have shown that AKT1, TICRR, PPIF, ANO1, and PTGDS are possible regulators of endometrial cancer tumorigenesis." (PMID 39596419, 2024).
Esophageal Neoplasms (2 papers, 2014 to 2016). "We observed that ANO1 expression was positive in 38.1% (109/286) and 25.4% (77/303) of primary esophageal tumors from the two independent cohorts, respectively." (PMID 27016410, 2016).
gastric tumor (2 papers, 2019 to 2024). "Immunohistochemical staining with appropriate controls was positive for KIT and ANO1 (DOG1), confirming diagnosis of metastatic GIST from the initial gastric tumor." (PMID 31730471, 2019).
gastroparesis (2 papers, 2015 to 2019). Paralysis of the muscles of the stomach wall resulting in delayed emptying of the gastric contents into the small intestine. "However, not consistent with this interpretation is our previous and current study in which we did not detect any significant differences in expression of KIT, ANO1 or KITLG between the high BMI control subjects and the low BMI idiopathic gastroparesis subjects." (PMID 31221130, 2019).